TMPRSS4 (transmembrane serine protease 4)
Diseases named in the same sentence as TMPRSS4 in open-access papers (continued):
Sharing a sentence is not in itself a finding about the gene and the disease.
prostate carcinoma (continued). "We also reported that TMPRSS4 promotes proliferation of lung and prostate cancer cells via activation of AP-1 and Sp111,12, indicating that TMPRSS4 is positively involved in both proliferation and invasion, although these are not common roles of TTSP family members." (PMID 31292507, 2019). "Our previous finding that TMPRSS4 activates AP-1 led us to hypothesize that TMPRSS4 may contribute to the proliferative phenotype of prostate cancer cells." (PMID 27385093, 2016). "Similarly, TMPRSS4 moderately increased DU145 prostate cancer cell proliferation and moderately induced cyclin D1 expression in these cells." (PMID 27385093, 2016). "TMPRSS4 upregulates SLUG and cyclin D1 in prostate cancer cells by activating AP-1, leading to both invasion and proliferation." (PMID 37009799, 2023). "Endogenous TMPRSS4-expressing 22Rv1 and LNCaP clone FGC prostate cancer cells were transiently transfected with TMPRSS4-specific shRNA vectors." (PMID 34809669, 2021). "TMPRSS4 promoted anchorage-independent growth, ALDH activation, tumorsphere formation, and therapeutic resistance of prostate cancer cells." (PMID 34809669, 2021). "To examine TMPRSS4-mediated cellular function and activity of TMPRSS4 inhibitors, we first generated stable TMPRSS4-overexpressing DU145 prostate cancer cell lines." (PMID 31292507, 2019). "In this study, we report that TMPRSS4 induces Slug and cyclin D1 through AP-1 activation in PC3 prostate cancer cells, leading to both invasion and proliferation." (PMID 27385093, 2016). "In this study, we showed that TMPRSS4 upregulates SOX2 expression through the EMT-inducing transcription factors TWIST1 and SLUG, suggesting potential role for TMPRSS4/TWIST1–SLUG on acquisition of CSC traits and aggressive malignancy during prostate cancer progression." (PMID 34809669, 2021). "TMPRSS4 induced Slug, an epithelial-mesenchymal transition (EMT)-inducing transcription factor, and cyclin D1 through activation of AP-1, composed of c-Jun and activating transcription factor (ATF)-2, which resulted in enhanced invasion and proliferation of PC3 prostate cancer cells." (PMID 27385093, 2016).
non-small cell lung carcinoma (9 papers, 2011 to 2025). A group of at least three distinct histological types of lung cancer, including non-small cell squamous cell carcinoma, adenocarcinoma, and large cell carcinoma. "Transmembrane serine protease 4 (TMPRSS4) is responsible for invasion and proliferation of PCa cells and its elevated levels are associated with poor prognosis in several cancers including prostate, gastric, colorectal and non-small cell lung cancer." (PMID 37091854, 2023). "Circ_0076305 confers resistance to paclitaxel (PTX) in non-small cell lung cancer cells (NSCLCs) by sponging miR-936 and increasing transmembrane serine protease 4 (TMPRSS4) expression." (PMID 40710359, 2025). "In this study, we examined TMPRSS4 mRNA as well as protein expression in human non-small cell lung cancer." (PMID 22692880, 2012). "In this study, quantitative RT-PCR and protein staining were used to assess TMPRSS4 expression in primary non-small cell lung carcinoma (NSCLC) tissues and in lung tumor cell lines." (PMID 22692880, 2012). "Here, we successfully generated a TMPRSS4-specific rabbit polyclonal antibody and, in conjunction with qPCR, immunohistochemistry (IHC) and immunoblot analyses, explored TMPRSS4 expression and its potential as a therapeutic target in non-small cell lung cancers." (PMID 22692880, 2012).
breast carcinoma (8 papers, 2012 to 2022). "The present study investigated the function of TMPRSS4 in the breast cancer cells and the potential mechanistic action underling." (PMID 31244309, 2019). "From this study, we showed that cell apoptosis and telomeres are implicated in TMPRSS4 expression modulation induced modulation of cells proliferation while cell cycle is only implicated in TMPRSS4 expression silencing reduced cell proliferation in breast cancer." (PMID 31244309, 2019). "TMPRSS4 is overexpressed in breast cancer cells, and its overexpression promoted the proliferation, migration, and invasion of breast cancer cells and is related to poor prognosis." (PMID 32695668, 2020). "Recently, we found that TMPRSS4 was overexpressed in breast cancer tissue, but few studies document the expression of TMPRSS4 in TNBC and non-TNBC, especially in TNBC." (PMID 23857060, 2013). "To date, several genes and their products have been introduced to predict the prognosis of breast cancer patients, such as transmembrane protease serine 4 (TMPRSS4), c-Kit, and syndecan-1 (SDC1)." (PMID 24373193, 2013). "Effect of TMPRSS4 modulation on breast cancer cells proliferation." (PMID 31244309, 2019). "In conclusion, our findings indicate that TMPRSS4 expression modulation modulates breast cancer cell proliferation by modulating cell apoptosis and telomere maintenance while cell cycle is only implicated in TMPRSS4 silencing mediated inhibition of breast cancer cells proliferation." (PMID 31244309, 2019). "TMPRSS4 plays important roles in cancer progression and may be considered as a good therapeutic target for cancer gene therapy especially breast cancer." (PMID 31244309, 2019). "Based on these data, we propose that TMPRSS4 may be an attractive and promising therapeutic target for breast cancer patients, especially in TNBC patients." (PMID 23857060, 2013). "However, the effect of TMPRSS4 on cell proliferation in relationship with telomere integrity remains unclear, especially in breast cancer." (PMID 31244309, 2019). "However, TMPRSS4 functions in breast cancer remain poor understand." (PMID 31244309, 2019). "Patients with high expression of TMPRSS4 had shorter overall survival (OS) and disease-free survival (DFS) in breast cancer." (PMID 36380313, 2022). "From our results, we demonstrated the negative correlation between TMPRSS4 expression and TNBC sensitivity to irradiation suggested that TMPRSS4 could be considered as a potential therapeutic target for enhancing breast cancer radiotherapy efficacy especially the triple negative breast cancer." (PMID 31870109, 2019).
COVID-19 (8 papers, 2021 to 2024). A disease caused by infection with severe acute respiratory syndrome coronavirus 2. "The interaction between TMPRSS2 and TMPRSS4 in the context of COVID-19 suggests a synergistic effect on cancer development, possibly through enhancing the ability of cancer cells to invade and metastasize." (PMID 39350850, 2024). "TMPRSS2 was found to favor the immune escape of COVID-19, and TMPRSS4 was upregulated in malignancies of the stomach, liver, and prostate." (PMID 36046240, 2022). "In addition, SLC6A20 expressionwas positively correlated with COVID-19-associated genes, ACE2, TMPRSS2,and TMPRSS4, in a number of tumor samples." (PMID 37041751, 2023). "There is a study on the pathogenesis of COVID-19 that reports that there is an interaction between TMPRSS2 and TMPRSS4 in small intestinal epithelial cells." (PMID 39350850, 2024). "The significance of TMPRSS4 with similar function as TMPRSS2 in viral infection, has been suggested in smokers and its relation to COVID-19." (PMID 37041586, 2023). "However, recent research has highlighted its role in COVID-19, revealing that key host factors for SARS-CoV-2 (Ace2 and Tmprss4) are upregulated in Elf5-overexpressing AT2 cells." (PMID 39175753, 2024).
viral infection (6 papers, 2022 to 2025). "The expression of the ACE2 and TMPRSS4 genes (both associated with viral infection) in the human endometrium may facilitate SARS-CoV-2 infection." (PMID 40556827, 2025). "Due to the positive correlation of TRIM31 with TMPRSS2 and TMPRSS4 genes, it may therefore cause higher susceptibility of viral infections, such as SARS-CoV-2, seen in cancer patients." (PMID 35970857, 2022). "Furthermore, transmembrane protease serine 4 (TMPRSS4) is reported to activate SARS-CoV-2 S proteins along with TMPRSS2, and enable viral infection of the human small intestine." (PMID 35632833, 2022).
hepatocellular carcinoma (5 papers, 2013 to 2023). A malignant tumor that arises from hepatocytes. "Overexpression of TMPRSS4 has a critical role in radiation-induced long-term dissemination and metastasis of residual hepatocellular carcinoma by facilitating epithelial-mesenchymal transition (EMT)." (PMID 23922976, 2013). "However, little is known about the biological effects of TMPRSS4 on hepatocellular carcinoma (HCC) and the related mechanisms." (PMID 26190376, 2015). "The membrane-bound serine protease TMPRSS4 induces EMT in colon and hepatocellular carcinoma cells, which is accompanied by upregulation of ZEB2, SNAIL, and SLUG8,9." (PMID 37009799, 2023). "However, the biological functions of TMPRSS4 have not yet been elucidated in hepatocellular carcinoma (HCC)." (PMID 26190376, 2015).
influenza (5 papers, 2012 to 2025). An acute viral infection of the respiratory tract, occurring in isolated cases, in epidemics, or in pandemics; it is caused by serologically different strains of viruses (influenzaviruses) designated A, B, and C, has a 3-day incubation period, and usually lasts for 3 to 10 days. "ACE2 receptor downregulation occurred specifically in females in Th2 high asthma, while proteases broadly assisting coronavirus and influenza viral entry, TMPRSS2, and TMPRSS4, were highly upregulated in both sexes." (PMID 34198852, 2021). "Our observations also suggest that TMPRSS2 can support influenza virus spread in species integral to the influenza zoonosis, and that mice are suitable models to study the role of TMPRSS2, TMPRSS4 and HAT in viral spread and pathogenesis." (PMID 22558251, 2012). "Using the Human Cell Atlas consortium respiratory single-cell RNA-seq data (reflecting the transcriptome of uninfected cells), we compared the expression of proteases previously identified to activate influenza HA: TMPRSS2, TMPRSS4, matriptase/ST14, HAT/TMPRSS11D, and furin." (PMID 40882005, 2025). "While the physiological role of CAP2/Tmprss4 is largely unknown due to lack of a knockout model, CAP2/Tmprss4 was identified as involved in pathologies such as cancer, influenza infections and neurological disorders." (PMID 26309024, 2015).
lung fibrosis (5 papers, 2018 to 2023). "The two most significant predictions from the SEA search for targets of niclosamide include KCNMA1 (calcium-activated potassium channel subunit alpha-1) and TMPRSS4 (transmembrane protease serine 4), both of which have been associated with pulmonary fibrosis." (PMID 34078171, 2021). "Furthermore, TMPRSS4 deficiency attenuates bleomycin-induced lung fibrosis in mice." (PMID 37009799, 2023). "Similar to IPF, in the mouse model of lung fibrosis TMPRSS4 was also observed in epithelial cells and more strongly in mast cells." (PMID 29529050, 2018). "TMPRSS4 is upregulated in the lungs of IPF patients and in a bleomycin-induced pulmonary fibrosis mouse model." (PMID 37009799, 2023).
triple-negative breast carcinoma (5 papers, 2013 to 2021). An invasive breast carcinoma which is negative for expression of estrogen receptor (ER), progesterone receptor (PR), and human epidermal growth factor receptor 2 (HER2). "In the present study, we found that TMPRSS4 down-regulation improved the apoptosis effect of ionizing radiation on triple negative breast cancer associated with inhibition of expression of Bcl2 and increased of Bax and Caspase3." (PMID 31870109, 2019). "In conclusion, our results indicated that down-regulation of TMPRSS4 improved triple negative breast cancer radiosensitivity via cells arrested in G2/M phase and increase of cells apoptosis ability." (PMID 31870109, 2019). "In the present study, the stable TMPRSS4 down-regulating TNBC cell lines were used to explore the role of TMPRSS4 on triple negative breast cancer radiosensitivity in relationship with cell cycle and cell apoptosis." (PMID 31870109, 2019). "After transfection of MDA-MD-468 triple negative breast cancer cells line by using the lentivirus vector, the effect of TMPRSS4 down-regulation on TNBC radiosensitivity was evaluated by using cloning assay and CCK-8 assay." (PMID 31870109, 2019). "The present study aims to investigate the role of TMPRSS4 in triple negative breast cancer (TNBC) cell radiosensitivity." (PMID 31870109, 2019). "Down-regulation of TMPRSS4 increases triple negative breast cancer cell radiosensitivity and the use of TMPRSS4 inhibitor can be encouraged for improving radiotherapy effectiveness in TNBC radioresistant patients." (PMID 31870109, 2019). "However, the function of TMPRSS4 in cancer cell radiosensitivity especially the triple negative breast cancer remains unclear." (PMID 31870109, 2019). "In triple-negative breast cancer (TNBC), TMPRSS4 inhibited TNBC apoptosis induced by 6 Gy IR, and the expression of Bax and Caspase 3 was overexpressed, while the expression of Bcl2 was downregulated, and radiotherapy sensitivity was decreased." (PMID 34528498, 2021).
lung adenocarcinoma (4 papers, 2012 to 2023). A carcinoma that arises from the lung and is characterized by the presence of malignant glandular epithelial cells. "Interestingly, 50% of the lung adenocarcinomas demonstrated moderate to marked TMPRSS4 staining (IHC score of ≥2), while only 20% of the lung squamous cell carcinomas showed similar staining intensity." (PMID 22692880, 2012). "For example, other cancer types such as Lung Adenocarcinoma (LUAD) or Liver Hepatocellular Carcinoma (LIHC) may also exhibit increased susceptibility to COVID-19 infection via similar mechanisms governed by TMPRSS2, TMPRSS4, and TRIM31, however this remains to be further investigated." (PMID 35970857, 2022). "To this end, we carried out large-scale correlation analyses across 5 public databases and found that 362 genes were significantly coexpressed with TMPRSS4 in lung squamous carcinoma (LUSC) and 48 in the case of lung adenocarcinoma (LUAD), in all databases." (PMID 31659178, 2019). "Rabbit polyclonal anti-TMPRSS4 antibody produced positive staining in tumor tissue sections from lung adenocarcinomas and squamous cell carcinomas but not in sections from samples of normal lung tissue or congested, hyperplastic, pulmonary edema or collapsed lung tissue sections." (PMID 22692880, 2012).
squamous cell carcinoma (4 papers, 2008 to 2013). A carcinoma arising from squamous epithelial cells. "Expression of TMPRSS4 in tumours with squamous cell carcinoma (SCC) histology was found to be significantly higher than those with adenocarcinoma (AC) histology." (PMID 23922976, 2013). "TMPRSS4 transcript was highly expressed in adenocarcinomas and squamous cell carcinomas, while expression in the normal tissues was negligible and only low levels were seen in large cell carcinomas." (PMID 22692880, 2012). "Differences in TMPRSS4 mRNA levels were statistically significant (p=0.0006) with 99% confidence intervals for Kruskal-Wallis test, and Dunn’s post-test displayed p<0.01 for normal vs. adenocarcinoma and normal vs. squamous cell carcinomas." (PMID 22692880, 2012). "We find that primary basal cell carcinomas, squamous cell carcinomas and thin melanomas express dramatically higher levels of many genes, including SPRR1A/B, KRT16/17, CD24, LOR, GATA3, MUC15, and TMPRSS4, than metastatic melanoma." (PMID 18442402, 2008). "In addition, staining of human squamous cell carcinoma samples for carbonic anhydrase IX (CAIX), a hypoxia marker, showed TMPRSS4 positive cells adjacent to CAIX positive cells." (PMID 22692880, 2012). "Because a reliable antibody against TMPRSS4 is not yet available, we evaluated mRNA levels of this protease by qRT–PCR in a clinical sample set including normal (n=15) and NSCLC (n=30; 11 AC+18 SCC+1 sarcomatoid epidermoid carcinoma histology) samples." (PMID 22067904, 2011).
bladder cancer (3 papers, 2018 to 2023). "In contrast to previously reported results for multiple other types of cancer, our study finds that high expression of TMPRSS4 predicts a better clinical outcome in bladder cancer, and this finding has been proven in previous studies." (PMID 37965307, 2023). "On the contrary, TMPRSS4 has a significantly strong positive correlation with genes in epithelial pathways (r = 0.61, p < 0.0001) but is opposite to the mesenchymal process in bladder cancer (r = −0.36, p < 0.0001)." (PMID 32695668, 2020). "CORO1C and TMPRSS4 might be two meaningful clinical indicators in bladder cancer but appear to have opposite prognostic value." (PMID 32695668, 2020). "The relationship between TMPRSS4 expression level and clinical traits also supports the protective role of TMPRSS4 in bladder cancer, which might be related to its counteractive function in the EMT process." (PMID 32695668, 2020). "Interestingly, in contrast to most cancer types in published research, our study finds that high expression of TMPRSS4 predicts a better clinical outcome in bladder cancer, and this finding has been verified in three data sets (two online and one from our center)." (PMID 32695668, 2020). "We downloaded another online data set, GSE19915, which included 144 bladder cancer patients to test the prognostic performance of these genes, but only three genes (CORO1C, TMPRSS4, and ZNF692) could match the probes in later survival analysis." (PMID 32695668, 2020). "The total alteration frequency is included to illustrate that CORO1C and TMPRSS4 are altered in 4.2% cases, which looks relatively not much higher in bladder cancer." (PMID 32695668, 2020). "Our own sequencing data found that the expression level of COMP/DPYSL2 in bladder cancer cases with response to tislelizumab combined with nab-paclitaxel therapy significantly decreased after treatment; however the expression level of TMPRSS4 increased after treatment in non-responsive cases." (PMID 37965307, 2023).
autosomal recessive cerebral atrophy (2 papers, 2015 to 2018). "CAP2/Tmprss4 was found mutated in a new form of pediatric neurodegenerative disorder, termed Autosomal Recessive Cerebral Atrophy (ARCA), where a point mutation in the gene (c.995C>T) leads to severe CNS degeneration." (PMID 26309024, 2015). "Studies in non-neoplastic diseases are scanty but it has been shown that TMPRSS4 may contribute to influenza virus replication and spread, and that a mutation of this protein causes a novel pediatric neurodegenerative disorder named autosomal recessive cerebral atrophy (ARCA) syndrome." (PMID 29529050, 2018).
large cell carcinoma (2 papers, 2011 to 2012). A malignant epithelial neoplasm composed of large, atypical cells. "The TMPRSS4 was highly expressed in 14 cell lines: Eight of them were derived from AC (H441, H2087, CALU3, H1648, HCC827, H358, PC14 and H322), one from SCC (H2170), three from SCLC (H187, H209 and H510), one from large cell carcinoma (97TM1) and one from carcinoid (H727)." (PMID 22067904, 2011).
lung squamous cell carcinoma (2 papers, 2012 to 2020). "In lung squamous cell carcinoma, overexpressed TMPRSS4 is associated with disease recurrence and poor survival by promoting invasion and metastasis." (PMID 32695668, 2020). "Frozen tissue sections of human lung squamous cell carcinoma were stained with rabbit polyclonal anti-TMPRSS4 and mouse monoclonal anti-CAIX, and then with DAPI for nuclei." (PMID 22692880, 2012).